NOP2 (NOP2 nucleolar protein)
Diseases named in the same sentence as NOP2 in open-access papers (continued):
Sharing a sentence is not in itself a finding about the gene and the disease.
tumor (continued). "Eventually, our qRT-PCR results showed that tumor tissues had higher NOP2 and NSUN6 expression levels and lower TET2 expression than normal tissues of ccRCC samples." (PMID 35309925, 2022). "We then identified tumor mutation burden (TMB), microsatellite instability (MSI), and NOP2 activity-mediated dysregulation of NOP2." (PMID 35372330, 2022). "Emerging research suggests that NOP2 is a multifunctional protein, which plays an important role in RNA modification and maturation, tumor invasiveness, cell cycle progression, chromatin organization, and HIV latency." (PMID 35372330, 2022). "Both the NOP2 mRNA and protein/phosphoprotein had a higher expression in ccRCC tumor tissues than in normal kidney tissues (both P < 0.001) and elevated NOP2 expression was associated with poor OS (P < 0.001)." (PMID 34334108, 2021). "Boxplot from TCGA ccRCC dataset further indicated that NOP2 had a high expression in ccRCC tumors, compared with normal kidney tissues (P = 3.494e-13, Normal = 72 and Tumor = 539)." (PMID 34334108, 2021). "NOP2 expresses at the higher level in the majority of human malignant tumor cells, and is considered as a prognostic marker for cancer aggressiveness." (PMID 32176734, 2020). "Earlier studies indicate that NOP2 is a multifunctional protein, which plays an important role in cell proliferation, cell-cycle progression, tumor aggressiveness, maturation and modification of RNA, as well as chromatin organization." (PMID 32176734, 2020). "Both APEX1 and NOP2 are recognized regulators of tumor metastasis, suggesting a potential mechanism wherein the lymphatic metastasis associated with high MGST1 could be attributed to the overexpression of either APEX1 or NOP2." (PMID 40778224, 2025). "Notably, adenovirus-mediated NOP2 knockout maximized the anti-tumor effect and prolonged the survival of patient-derived tumor xenograft (PDX) mice." (PMID 41462962, 2025). "To further unveil whether the tumor-promoting effects of NOP2 were dependent on ALYREF, we performed western blot and transwell assays." (PMID 39013911, 2024). "Moreover, NOP2 overexpression increased tumor size and weight in subcutaneous ccRCC mice; however, these effects were mitigated by APOL1 knockdown." (PMID 39309431, 2024). "Next, to further investigate whether c-Myc was involved in NOP2-mediated tumor proliferation and metastasis, a rescue assay was performed." (PMID 37398932, 2023). "Our findings demonstrated the beneficial effect of NOP2 inhibitors on tumor growth in patients with HCC and indicated the possibility of using them in combination with sorafenib, thereby facilitating the development of anti-HCC drugs and therapeutic strategies in the future." (PMID 37398932, 2023). "The tumor weight was remarkably decreased in the NOP2-KO group compared with the WT group." (PMID 37398932, 2023). "As protein phosphorylation had been revealed to play vital roles in multiple cancers, we also analyzed the NOP2 phosphoprotein expression and found that it was highly expressed in primary ccRCC tumor than normal tissues with phosphorylation sites at the S58, T191 and S728." (PMID 34334108, 2021). "Moreover, the activity and expression of NOP2 were higher in tumor tissues than in normal tissues." (PMID 35372330, 2022). "Furthermore, research in the mechanism found PVT1 could target genes such as LASP1, FOXM1, RSPO1, p15, p16, EZH2, TSHR, and NOP2 to promote tumor cell proliferation, migration and invasive capability in vitro." (PMID 29088881, 2017). "In order to more intuitively demonstrate the important value of NOL1/NOP2/SUN domain (NSUN) family genes in both tumor and non-tumor diseases, we conducted a relevant review." (PMID 41462962, 2025). "This study provides the first experimental evidence revealing that NOP2‐dependent m5C modification of LMNB2 mRNA increases the LMNB2 protein expression by enhancing its mRNA stability, thereby facilitating CRC tumor growth and metastasis." (PMID 40366008, 2025).
tumor (continued). "Here, to further confirm the function of NOP2 for CRC, we detected the NOP2 expression in COAD and READ tumor tissues and adjacent normal tissues." (PMID 40366008, 2025). "NOP2 nucleolar protein (NOP2, also known as NSUN1) is important in accelerating cell proliferation, cell cycle progression, and tumor invasiveness, and is abnormally expressed in cancers." (PMID 41462962, 2025). "NOP2, NSUN2, and NSUN4, key RNA m5C methyltransferases, are highly expressed in NSCLC tumour tissue, and their levels are strongly correlated with tumour grade, tumour size, and poor outcomes." (PMID 40860147, 2025). "These miRNAs act as tumor suppressors, and PVT1 sponging them induces the expression of their target gene, NOP2 nucleolar protein (NOP2), a metastasis-related protein." (PMID 36831169, 2023). "The qRT-PCR results indicated that NOP2 was markedly up-regulated in the HCC tissues and was correlated with higher tumor–node–metastasis (TNM) stage portal vein tumor thrombus, and tumor size." (PMID 37398932, 2023). "In clear cell renal cell carcinoma (ccRCC), the mRNA levels of NOP2 and NSUN4 are higher in tumor tissues than in normal tissues, whereas the mRNA levels of NSUN6 and m5C eraser TET2 are lower." (PMID 35562754, 2022). "Our qRT-PCR analysis revealed elevated expression levels of NOP2 and NSUN6, but decreased expression of TET2 were in the tumor tissues compared to those in the paired normal tissues of 15 ccRCC samples obtained from FPH (p < 0.05)." (PMID 35309925, 2022). "In the present study, qRT-PCR data from 15 paired FPH ccRCC samples revealed that while NOP2 and NSUN6 were upregulated, TET2 was downregulated in tumor tissues compared with those in normal tissues." (PMID 35309925, 2022). "NOP2/NSUN1 is overexpressed in a wide variety of cancer, and its expression level correlates with tumor aggressiveness, poor prognosis and therapy resistance." (PMID 36161484, 2022). "We further verified the expression of NOP2 in the ICGC dataset and found that it also had a high expression in tumor tissues, compared with normal tissues (P = 5.062e-15; Normal = 45 and Tumor = 91)." (PMID 34334108, 2021). "In summary, lncRNA-LINC00963 functions as a ceRNA that competitively binds to miR-542-3p, which then up-regulates NOP2 and promotes PCa metastasis via activating EMT signaling, which is the critical pathway regulating tumor metastasis in several cancers." (PMID 32554858, 2020). "NOP2 is an oncogene in ccRCC that promotes proliferation, migration, and invasion, relying on m5C to stabilize APOL1 and regulate the PI3K–AKT signaling pathway by promoting tumor progression." (PMID 41462962, 2025). "Notably, in a patient-derived tumor xenograft (PDX) model, adenovirus-mediated knockout of NOP2 maximized the antitumor effect and prolonged the survival of PDX-bearing mice." (PMID 37398932, 2023). "In addition, we also analyzed the expression of NSUN members in GSE46602, NOP2 and NSUN2 were highly expressed in tumor tissues, and NSUN4 was lowly expressed." (PMID 35978830, 2022). "NOP2(p120) is a putative RNA methyl transferase protein and its expression is detectable in proliferating normal and tumour cells, but undetectable in non-proliferating normal cells." (PMID 31712650, 2019). "Moreover, five writers (NOP2, NSUN2, NSUN3, NSUN4 and NSUN5), one reader (ALYREF) and two erasers (TET2 and TET3) were consistently upregulated in UCB tumor tissues compared to adjacent normal tissues from TCGA cohort (fold change > 1.1, P-value <0.05, occurrence rate > 50%)." (PMID 36806253, 2023). "However, NOP2 expression was not related to age, gender, and tumor stage in resected LUAD, which was not in accordance with our study." (PMID 35372330, 2022).
tumor (continued). "The expression of ALKBH1 (p = 0.036), ALYREF (p < 0.001), NOP2 (p < 0.001), NSUN2 (p < 0.001), NSUN4 (p < 0.001), NSUN5 (p < 0.001), NSUN6 (p < 0.001), NSUN7 (p = 0.006), and YBX1(p < 0.001) were significantly upregulated in tumor tissues compared with the adjacent mucosa." (PMID 35281843, 2022). "Notably, the role of NOP2 in the reprogramming of tumor glucose metabolism has not been reported." (PMID 37398932, 2023). "Additionally, we found that essential passenger genes, including NOP2, DCTN6 and FOXD4, were associated with closed chromatin and increased DNA methylation at the same respective loci when amplified compared to when not amplified in tumor PDCs compared to normal PDCs." (PMID 40931149, 2025). "Both in-frame fusions from advanced disease, ESR1-e6>YAP1 and ESR1-e6>PCDH11X, promoted estrogen-independent growth (−E2), but the primary tumor fusion event, ESR1-e6>NOP2, had no growth-promoting properties." (PMID 30089255, 2018).
cancer (35 papers, 2019 to 2026). A tumor composed of atypical neoplastic, often pleomorphic cells that invade other tissues. "Previous studies have shown that NOP2 was notably up-regulated in most cancers, and high NOP2 expression was associated with poor prognosis." (PMID 37398932, 2023). "As a result, ccRCC patients with elevated NOP2 expression were easily associated with cancer progression." (PMID 34334108, 2021). "NOP2 expression correlated significantly with mast cell infiltration in 24 cancer types and CD8+ T-cell infiltration in 19 cancer types (P < 0.05)." (PMID 42136761, 2026). "Through exploring the GEPIA2 database, we found high expression of NOP2 in various kinds of cancers." (PMID 40366008, 2025). "Previous research suggests that the expression of NOP2 primarily relies on the m5C methylation level, as it can promote cancer cell proliferation through m5C-dependent inhibition of Cyclin-Dependent Kinase Inhibitor 1B (CDKN1B, p27Kip1)." (PMID 38436027, 2024). "Although human NOP2/NSUN1 has been known to be an oncogene overexpressed in several types of cancer, its functions and substrates remain poorly characterized." (PMID 36161484, 2022). "To understand the potential roles of NOP2 in 33 cancers, we conducted a systematical study on the characteristics of expression, prognosis, and TME of NOP2 from The Cancer Genome Atlas (TCGA) and Gene Expression Omnibus (GEO) databases." (PMID 35372330, 2022). "Previous studies have demonstrated that some m5C regulators participate in the malignant progression of cancer such as NOP2 and YBX1." (PMID 34394351, 2021). "In this risk score signature, four genes (NOP2, NSUN4, NSUN5, and NSUN7) were cancer-promoting and NSUN6 was a cancer-suppressor gene." (PMID 32974125, 2020). "Human NSUN1 (also termed NOP2/ nucleolar antigen p120) was found to be strongly overexpressed in multiple human cancers, while normal cell types exhibit low expression levels." (PMID 30311405, 2019). "By regulating rRNA processing and function, NOP2/NSUN1 may influence ribosome synthesis and promote cancer cell proliferation." (PMID 39802639, 2025). "Furthermore, the MYC, DDX21, USP7, RFC4, APEX1, CDK9, and NOP2 of the “cancer cells_vs_all-PDAC” group play a critical role in the metabolic reprogramming of the PDAC, contributing to the poor prognosis of PDAC." (PMID 40906153, 2025). "Additionally, NOP2 was upregulated in cancer cells (n = 90) than in control cells in the International Cancer Genome Consortium (ICGC)-ccRCC cohort (n = 45) and the paired TCGA-KIRC cohort (n = 72)." (PMID 39309431, 2024). "TCGA pan-cancer data showed that NOP2 is overexpressed in various types of human cancers, suggesting that NOP2 may function as a common oncogene involved in tumorigenesis and progression, including ccRCC." (PMID 39309431, 2024). "This indicated that NOP2 might have an indirect effect on the immunotherapeutic response of these cancers." (PMID 35372330, 2022). "Gene Ontology (GO) analysis suggested that NOP2 was mainly concentrated in the olfaction, angiogenesis and regulation, RNA polymerase, and membrane methyltransferase potential and transport in the four types of cancers." (PMID 35372330, 2022). "5-methylcytosine (m5C) modification, which is mainly induced by the RNA methyltransferase NSUN2 (NOP2/Sun domain family, member 2), is an important chemical posttranscriptional modification in mRNA and has been proven to play important roles in the progression of many cancers." (PMID 36792587, 2023). "Thus, clarifying the biological roles of NOP2 in cancers may help identify useful markers for clinical diagnosis and therapeutic treatment." (PMID 35372330, 2022). "The protein network of unique cancer cell genes in the “cancer cells_vs_all-PDAC” group exhibited top 10 hub genes, including H4C6 (HIST1H4A or HIST1H4C), MYC, H3C12 (HIST1H3A or HIST1H3D), DDX21, USP7, RFC4, APEX1, CDK9, H2BC9 (HIST1H2BH), and NOP2." (PMID 40906153, 2025).
cancer (continued). "RNA methyltransferase nucleolar protein p120 (NOP2), commonly referred to as NOP2/Sun RNA methyltransferase family member 1 (NSUN1), is involved in cell proliferation and is highly expressed in various cancers." (PMID 37800580, 2023).
infection (2 papers, 2020 to 2021). The state of being infected such as from the introduction of a foreign agent such as serum, vaccine, antigenic substance or organism. "Overexpression of NOP2 in MAGI-HeLa cells reduced the infection of VSV-G pseudo-typed HIV-1 NL4-3-Luc (dEnv) viruses by ~50%." (PMID 32176734, 2020). "Depletion of NOP2 by its siRNA increased the infection rate of HIV-1 IIIB by over 3 folds." (PMID 32176734, 2020).
neurodevelopmental disorder (2 papers, 2019 to 2020). A behavioral and cognitive disorder with onset during the developmental period that involves impaired or aberrant development of intellectual, motor, or social functions. "Similarly, mutations in the family of NOL1/NOP2/sun (Nsun) domain-containing genes encoding RNA methyltransferases in humans are associated with neurodevelopmental disorders." (PMID 32765591, 2020).
NOP2 also shares sentences with these, for which no sentence is quoted: Bladder Cancer (2 papers); glioblastoma (2); acute myeloid leukaemia (1); Anxiety (1); cervical cancer (1); cutaneous melanoma (1); depression (1); endometrial cancer (1); esophageal cancer (1); gallbladder cancer (1); gastric adenocarcinoma (1); Gynecologic cancers (1); head and neck squamous cell carcinoma (1); HIV-1 infection (1); lung squamous cell carcinoma (1); malaria (1); malignant glioma (1); melanoma (1); mental retardation (1); monocytic leukaemia (1); myelodysplastic syndrome (1); neuroblastoma (1); neurological disease (1); pancreatic cancer (1); prostate tumor (1); pulmonary fibrosis (1); refractory anaemia (1); septic shock (1); spinocerebellar ataxia type 1 (1); Spinocerebellar ataxia type 3 (1).
A further 1 disease shares a sentence with NOP2 in 1 paper.